TNF (tumor necrosis factor)
Diseases named in the same sentence as TNF in open-access papers (continued):
Sharing a sentence is not in itself a finding about the gene and the disease.
leprosy (continued). "A stratified subgroup analysis based on the ethnicity of the enrolled subjectswas performed to explore the effect of ethnicity (Asian and Latin American) onthe relationship between TNF -308 G>A gene polymorphismand the risk of leprosy development." (PMID 28935761, 2017). "For instance, genes associated with innate immune response, like TLR1, NOD2, and PARK2 or adaptive immune responses, such as IL10, IFNG and LTA/TNF/HLA have been consistently associated with leprosy." (PMID 25187983, 2014). "Another study reported a higher bacteriological index in patients with leprosy carrying the TNF-238A allele." (PMID 21408088, 2011). "tumor necrosis factor-alpha inhibitor use may be a risk factor for developing leprosy or reactivating subclinical infection." (PMID 38716298, 2024). "Carriers of the miR-146a C allele have been shown to express high levels of mature miR-146a coupled to a reduced expression of TNF (Tumor Necrosis Factor) with a susceptibility to leprosy; suggesting that miR-146a negatively influences the secretion of TNF by controlling its level of expression." (PMID 34737736, 2021). "Recently developed immunosuppressive drugs, especially TNF antagonists, may enhance the risk of granulomatous infections, including leprosy." (PMID 33849463, 2021). "IFN-γ, TNF and IL-10 are mediators traditionally associated with leprosy pathogenesis per se." (PMID 27764137, 2016). "In both cases lower TNF levels correlates with subjects carrying the risk C-allele, (p = 0.0453 and p = 0.0352; respectively), which is consistent with an immunomodulatory role of this miRNA in leprosy." (PMID 25187983, 2014). "According to authors, the combination of low T-cell inhibition status of BTNL2, less inhibition of TNF by BAT1, and low TNF expression may provide protection from leprosy, which may be stronger in the presence of high TNF producer allele genetic background." (PMID 23936864, 2013). "However, anti-TNF-α biologics are associated with a potential risk of leprosy, and directly increasing IFN-γ levels in cases of multibacillary disease may trigger adverse reactions in patients." (PMID 41306590, 2025). "Interestingly, a large association study conducted in four Brazilian population samples, followed by a meta-analysis including additional genotypes from published data, reinforced the TNF − 308 protective effect in leprosy and suggested that the association is restricted to the Brazilian population." (PMID 30116885, 2018). "According to authors, the combination of low T-cell inhibition status of BTNL2, less inhibition of TNF-α by BAT1, and low TNF-α expression may provide protection from leprosy, which may be stronger in the presence of high TNF-α producer allele genetic background." (PMID 26793196, 2015). "However, excess TNF-α can cause tissue damage in diseases such as rheumatoid arthritis and inflammatory bowel disease, and thus this cytokine plays a key role in tissue damage in leprosy." (PMID 22180790, 2011). "Studies have revealed that manipulating cytokines, such as IFN-γ, TNF-α, and GM-CSF, offers therapeutic advantages, especially in the more severe forms of leprosy." (PMID 41306590, 2025). "Bezerra-Santos and colleagues have shown that TNF levels correlate with the clinical outcome of patients with leprosy." (PMID 39744632, 2024). "Elevated circulating levels of TNF are observed in the multibacillary form of leprosy, suggesting a significant involvement of this biomarker in the pathogenesis of the disease." (PMID 39744632, 2024). "Serum-sTREM-1 and TNF-α levels were measured in leprosy patients (LP) before treatment (n = 51) and from their household contacts (HHCs; n = 25)." (PMID 37457576, 2023). "TNF-α has been related to demyelination and axonal degeneration as well as immune cell recruitment to the injury site and, in leprosy, it has been detected in reactional states." (PMID 38116016, 2023).
leprosy (continued). "Taken together, our analyses indicated that sTREM-1 and TNF-α play an important role in the pathogenesis of leprosy and provide promising biomarkers to assist in the diagnosis of leprosy complications." (PMID 37457576, 2023). "As an important example, TNF-α expression is related to intense phagocytic activity, which is also observed in type I leprosy reactions." (PMID 33819170, 2021). "Cytokines level before the introduction of vaccination suggested that leprosy cured group have relatively high concentration of IL-6, IL-10, TNF, INF-γ and IL-17 compare to control group." (PMID 34397815, 2021). "Regarding leprosy, a main concern is the targeted use of anti-TNF compounds because they are responsible for reducing the granulomatous response, an important factor for the control of mycobacterial infection." (PMID 33849463, 2021). "At day 0, leprosy cured group have relatively high concentration of interleukin-6, interleukin-10, tumor necrosis factor, interferon-γ, and interleukin-17 compared to control group." (PMID 34397815, 2021). "Mutations occurred more often in the IL-10 (anti-inflammatory cytokine) promoter gene than in the TNF-α (pro-inflammatory) promoter gene in all leprosy groups." (PMID 32849660, 2020). "One report has shown that, in leprosy, TNF and TGF-β induce apoptosis in Schwann cells, with a consequent damage to peripheral nerve." (PMID 32038662, 2020). "The mechanism by which IFN-γ induces ENL reactions in patients with leprosy is suggested to be through priming of monocytes, resulting in enhanced TNF production." (PMID 29479352, 2018). "We analyzed the presence of M4 macrophage markers (CD68, MRP8, MMP7, IL-6, and TNF-α) in 33 leprosy skin lesion samples from 18 patients with tuberculoid leprosy and 15 with lepromatous leprosy by immunohistochemistry." (PMID 30442123, 2018). "TNFA and IL10 genetic variants are classic risk factors for leprosy; gene products TNF-α and IL-10 are major signature cytokines for the tuberculoid and lepromatous pole, respectively." (PMID 30079069, 2018). "A study showed that polymorphisms in the TLR1 gene changed the levels of tumor necrosis factor (TNF) and IL-10 in macrophages and were associated with a higher risk for developing leprosy in India and Brazil." (PMID 30289892, 2018). "Several genes have been associated with leprosy, such as NOD2, PARK2/PARCG, LRRK2, RIPK2, TNF/LTA/HLA, LACC1, IL10, TLR1, and microRNA (miR)-146a." (PMID 29755459, 2018). "In leprosy, both TNF-α and IFN-γ have been shown to bind to the cellular receptor of the macrophages, thereby changing the behavior of M0 macrophages, which undergo phenotypic modification to become M1 inflammatory macrophages." (PMID 29234318, 2017). "Since macrophages are the main cells that exert microbicidal activity in leprosy, many studies have already described the role of these cells in the response to cytokines, including tumor necrosis factor-alpha (TNF-α) and interferon-gamma (IFN-γ)." (PMID 29234318, 2017). "LTα and TNFα have been shown to play independent roles in the evolution of the granulomatous response in experimental leprosy because of their distinctive roles in the recruitment of lymphocytes." (PMID 29201923, 2017). "Although more frequent in ENL, previous studies indicated that TNF mediates immune-pathologic effects, such as fever and tissue damage, in both type 1 and type 2 leprosy reactions." (PMID 27764137, 2016). "The study detected significant linkage of the 6p21 region, including TNF, with leprosy polarization." (PMID 27219008, 2016). "Among the common proinflammatory mediators identified in serum during the occurrence of leprosy reactions (a) and PD (b), IL-6 and TNF-α were predominant." (PMID 26339136, 2015). "For leprosy reactions, the most common proinflammatory mediators were TNF-α (7 articles), IFN-γ (5 articles), IL-6 (4 articles), and IL-17 (3 articles), and the most common anti-inflammatory mediators were IL-4 (4 articles) and IL-10 (4 articles)." (PMID 26339136, 2015).
leprosy (continued). "The extent of TNF-α inhibition in healthy subjects for methylprednisolone was 53.1% and in leprosy affected was 65.3%." (PMID 25070345, 2014). "Inhibition of TNF-α by steroid (DC) was 65.3% by in vitro as compared to 60% in vivo suggesting partial response in leprosy reactions." (PMID 25070345, 2014). "Studies have been carried out in order to investigate a possible combined effect of HLA genes and cytokines genes in leprosy, more specifically TNF gene and HLA class II." (PMID 23936864, 2013). "It would also be interesting to quantify TNF RNA levels and determine when they rise in relation to leprosy reactions." (PMID 22180790, 2011). "TNF-α protein was detected in 78% of skin biopsies taken from definite leprosy cases at baseline (181/233)." (PMID 22180790, 2011). "TNF-α protein has been detected in biopsies taken from leprosy patients with skin reactional lesions, both T1R and ENL." (PMID 22180790, 2011). "Although apoptotic proteins are activated in leprosy lesions from all patients, reports indicate that apoptosis is greater in PB disease, correlating with increased TNFα secretion." (PMID 16978419, 2006). "In 2020, a systematic review analyzed the incidence of leprosy in patients using anti-TNF." (PMID 38238209, 2024). "TNF is elevated in the blood of both PB and MB leprosy, and is observed in granulomatous lesions." (PMID 36972292, 2023). "In addition, cases of leprosy have increased globally, notably in patients undergoing treatment with TNF-α blockers and due to the increase in migration and travel of people from developing countries to developed countries." (PMID 37822467, 2023). "Studies have shown that PD-1/PD-L1 suppress IFN-γ against TNF-α in leprosy patients." (PMID 37153623, 2023). "We further select 7 cytokines and immune mediators to detect immune response after vaccination and found that before the onset of vaccination, leprosy cured group have relatively high concentration of IL-6, IL-10, TNF, INF-γ and IL-17 compared to control group." (PMID 34397815, 2021). "Here, we investigated whether SNPs located in eleven genes: CCDC122/LACC1, IFNG, IL6, IL10, IL23R, LRRK2, NOD2, PACRG/PRKN, TLR1, TNF and TYK2 are associated to leprosy susceptibility in a population in the North of Brazil." (PMID 32433683, 2020). "Moreover, the most frequently involved SNP of TNF in infectious diseases, TNF-308 G>A (rs1800629), has been widely studied in leprosy with different ethnicities, including Nepalese, Brazilians, and Indians." (PMID 32373110, 2020). "In the TT form of leprosy, activation of the classical pathway by M1 macrophages induces the production of tumor necrosis factor-alpha (TNF-α), interferon-gamma (IFN-γ), and induced nitric oxide synthase (iNOS), which induce the generation of free radicals that destroy the bacillus." (PMID 30442123, 2018). "In addition, IFN-γ priming of peripheral blood monocytes from patients with leprosy has been demonstrated to enhance TNF-α production, both in vivo and in vitro." (PMID 29479352, 2018). "The markers included 11 SNPs selected to replicate the previously reported associations of the TLR1, NOD2, and IL6 genes and the remaining SNPs in 4 candidate genes TNF, LTA, IFNG, and IL10, in reference to markers previously associated with leprosy per se as an outcome." (PMID 28715406, 2017). "After knowing the clinical significance of TNF in the severity ofclinical manifestation of various infectious diseases, including leprosy, it isimportant to explore its precise role in the development of leprosy." (PMID 28935761, 2017). "In addition, IFN-γ and TNF, two cytokines reported to increase in the T-lep form of leprosy, are able to induce autophagy." (PMID 28056107, 2017).
leprosy (continued). "In summary, regardless of the laboratory technique used and the type of sample analyzed, the identified proinflammatory mediators involved in the immune pathologic process of dental infections and leprosy reactions, particularly IL-6 and TNF-α, were similar in the studies reviewed." (PMID 26339136, 2015). "As clinical reactions are known to precede nerve damage, inhibition of S100 antibody and TNF-α in reaction could be a molecular mechanism by which reactions are controlled, thus facilitating a quick recovery of nerve function in leprosy." (PMID 25070345, 2014). "We therefore hypothesised that high TNF-α production might be a key part of the pathological process of leprosy reactions; then finding high levels of TNF-α in skin biopsies might be a marker for leprosy reactions." (PMID 22180790, 2011). "Skin and nerve are very different compartments and it may be that in the context of the leprosy damaged peripheral nerve TNFα leaks more easily into the circulation than from inflamed skin lesions." (PMID 21408123, 2011). "Previous studies have shown that TNFα is produced in skin and nerve during leprosy T1R." (PMID 21408123, 2011). "However, a serendipitous discovery revealed that Sildenafil has a significant therapeutic impact on erythema nodosum leprosum (a type of autoimmune complication of leprosy) by inhibiting the synthesis of the pro-inflammatory cytokine tumor necrosis factor-alpha (TNF-α)." (PMID 39206192, 2024). "Thus, it is possible that theclinical outcomes of leprosy are affected by the propensity of the host to produceTNF in response to the infection of M. leprae.Also, a previous study of TNF knockout mice showed thatTNF is indispensable for the resistance in infectious disease." (PMID 28935761, 2017). "Indeed, a strong host genetic contribution to leprosy susceptibility has been well established through the identification of leprosy susceptibility genes by both positional cloning (PARK2, LTA, HLA-C, MRC1) and candidate gene approaches (e.g. TLR1, TNF, CUBN and NEBL)." (PMID 28793313, 2017). "Moreover, reactivation of leprosy was reported in three patients who were using TNF-α antagonists." (PMID 22709461, 2012). "In addition, M. leprae-induced apoptosis in primary monocytes has been shown to be TNFα dependent, and inhibition of TNFα via treatment with anti-TNFα inhibitors or pentoxyfylline is found to reduce host inflammation and cell death in reactional leprosy." (PMID 16978419, 2006). "The identification of Th17 cells as major inducers of antimicrobial genes in RR lesions through the expression of TNF, IFNG, and IL17A provides important new insights into the role of this T cell subset in leprosy immunopathogenesis." (PMID 40569678, 2025). "Soluble mediator analysis, presented as biomarker concentrations in pg/mL, evaluated as continuous variables, revealed that leprosy patients and HHC exhibited elevated levels of TNF upon M. leprae-stimulated culture compared to EC." (PMID 39744632, 2024). "Although there were differences in production of IL-22, TNF-α and IFN-γ between lesions of TT leprosy and healthy controls, skin dermal γδ T cells mainly produced large amount of IL-17A." (PMID 36389696, 2022). "Increased MMP-2, MMP-9 mRNA, and protein MMP-9 levels were detected together with enhanced TNF-α and IFN-γ expression levels in the lesions of both tuberculoid patients and in those undergoing leprosy reactions like ENL." (PMID 34692720, 2021). "This supports previous studies which found that the autophagy inhibiting cytokine IL-10 is predominant in multibacillary leprosy compared to high levels of IL-26, IFN-γ, and TNF-α, autophagy inducing cytokines, found during paucibacillary tuberculoid leprosy." (PMID 33519771, 2020). "TNF and LTA were also suggested to play essential but different roles in the regulation of leprosy granuloma formation." (PMID 32373110, 2020).
leprosy (continued). "PCR analysis demonstrated the expression of inflammatory cytokines TNF, IL-6, and IL-12 besides high expression of ICAM-1 in the epidermis of reactional leprosy lesions." (PMID 29643852, 2018). "Previous findings support a correlation between the levels of TNF-α and LXA4/LTB4 ratio in leprosy patients." (PMID 29472920, 2018). "On the other hand, leprosy patients with T1R possess a lower LXA4/LTB4 ratio, which agrees with increased inflammation and higher levels of TNF-α observed in these patients." (PMID 29472920, 2018). "Early reports on leprosy showed increased expression levels of IL-22, IL-13, and FGF b in the lepromatous form, whereas an increase of TNF-α was more evident in the tuberculoid form." (PMID 29234318, 2017). "Neutrophils isolated from leprosy patients (ENL and BL/LL) released TNF-α and IL-8, after stimulation with lipopolysaccharide (LPS) or M. leprae." (PMID 28348555, 2017). "A recent study evaluated TNFα, anti-ceramide, anti-S100, IgG and IgM anti-PGL-I, IgG1 and anti-LAM IgG3 antibodies in leprosy patients before, during and after the reaction episode." (PMID 28222139, 2017). "Summary of associations between genes of innate immune response MICA, MICB, KIR, TNF, LTA, BAT1, IFNG, and leprosy." (PMID 26793196, 2015). "Based on the analysis of clinical specimens, we found that the genetic variant was correlated with elevated levels of miR-146a and it is also a negative regulator of tumor necrosis factor (TNF), an important inflammatory mediator in the leprosy context." (PMID 25187983, 2014). "There is ample evidence of the involvement of cytokines, especially tumor necrosis factor-alpha (TNF-α), in the immune response to leprosy." (PMID 23936864, 2013). "Beside IFN-γ, also IP-10, IL-6, IL-1β, TNF-α, and MCP-1 were increased in EC from areas with high leprosy prevalence in response to these ML1601c peptides." (PMID 22363349, 2012). "In severe leprosy reactions (ENL), TNF-α modulation shows the strongest clinical signal." (PMID 41306590, 2025). "Elevated circulating TNF has also been observed in patients with leprosy reactions as compared to patients without reactions, suggesting a role of TNF in acute inflammatory episodes in leprosy patients." (PMID 36972292, 2023). "Monocytes are rarely studied in ENL, although the expression of tumor necrosis factor (TNF)-α is higher in patients with MB leprosy with ENL than in those without ENL." (PMID 35324586, 2022). "A qPCR performed to evaluate pro- and anti-inflammatory related gene expression in skin lesions of leprosy patients revealed that pro-inflammatory genes STAT1, TNF, IFNG, IL15 and CSF2 are increased in PB cells, whereas anti-inflammatory MSR1 and PPARG genes are increased in MB cells." (PMID 34354699, 2021). "TNF and IL-6 levels were evaluated in serum samples from people affected by leprosy and UN with or without ulnar CB." (PMID 34797866, 2021). "To ascertain if the increased levels of IL-6 would be derived from reactional episodes or neuritis we selected the serum from leprosy patients without reactional episodes or neuritis and evaluated IL-6 and TNF levels by ELISA." (PMID 34797866, 2021). "Moreover, increased levels of TNF, TGF-β, and IL-17 in leprosy and neural pain patients have also been detected." (PMID 32038662, 2020). "We reported that neutrophils isolated from lepromatous leprosy patients with or without ENL release TNF and IL-8 after stimulation with M. leprae." (PMID 29643852, 2018). "The proinflammatory mediators in dental infections and leprosy reactions, especially IL-6 and TNF-α, were similar across studies, regardless of the laboratory technique and sample type." (PMID 26339136, 2015). "Seven serological markers [TNF-α, antibodies to Phenolic glycolipid-1 (PGL-1 IgM and IgG), Lipoarabinomannan (LAM IgG1 and IgG3), C2-Ceramide and S100 B] were analyzed longitudinally in 72 leprosy patients before, during and after the reaction." (PMID 25070345, 2014).